FOXA1 (forkhead box A1)
Diseases named in the same sentence as FOXA1 in open-access papers (continued):
Sharing a sentence is not in itself a finding about the gene and the disease.
infection (12 papers, 2013 to 2025). The state of being infected such as from the introduction of a foreign agent such as serum, vaccine, antigenic substance or organism. "Most lesions in KrasLSL-G12D/+; Nkx2-1F/F; Foxa1F/F; Foxa2F/F mice exhibited complete loss of FoxA1/2 expression when analyzed at 11 weeks post-infection." (PMID 30475207, 2018). "FOXA1 expression was determined using quantitative real-time PCR and western blot analyses with osteogenic induction for 3 and 7 days after infection and puromycin screening." (PMID 36064451, 2022). "We found that the newly discovered host anti-viral factor POLM could be regulated by FOXA1 in the infection process with PEDV." (PMID 39927776, 2025). "FOXA1 and SP1 were also upregulated during infection in both Vero E6 and Calu-3 cells, but their overexpression was not sufficient to trigger ZDHHC20Long production in HeLa cells." (PMID 37952051, 2023). "TP63, FOXA1, STAT1, ELK1, FOS, and JUN are TFs in various lung injury or infection types." (PMID 36911695, 2023). "For host interactions, MRPL50 via C. albicans WO-1 infection directly triggers TF FOXA1 but not protein MYC (also knowns C-Myc) in C. albicans SC5314 infection." (PMID 30769958, 2019).
adenocarcinoma (9 papers, 2014 to 2025). A common cancer characterized by the presence of malignant glandular cells. "Using transgenic mouse models, we show that FOXA1 Class 1 mutations trigger formation of invasive adenocarcinomas, while Class 2 mutations rewire the luminal cell identity to impart resistance to ADT." (PMID 40570057, 2025). "AdSCC in the KrasLSL-G12D/+; Nkx2-1F/F; Foxa1F/F mouse exhibited the opposite pattern, that is, FoxA1 loss in both components and FoxA2 expression only in the adenocarcinoma component." (PMID 30475207, 2018). "As expected, AdSCCs in KrasLSL-G12D/+; Nkx2-1F/F; Foxa1F/F; Foxa2F/F mice always expressed either FoxA1 or FoxA2 in the adenocarcinoma component and stochastic loss of the other paralogue in the squamous component." (PMID 30475207, 2018). "A 2005 study, which used LPR-Tag LADY transgenic PCa mice models, showed that FOXA1 was differentially expressed in prostate diseases, with upregulation in both pre-neoplastic lesions and adenocarcinomas." (PMID 34298646, 2021). "In the adjacent tissue sections, nuclei of those TSPY-positive adenocarcinoma cells were also positively stained by anti-FOXA1." (PMID 24528896, 2014). "FoxA1 and FoxA2 were expressed in the adenocarcinoma component of all cases." (PMID 30475207, 2018). "We next analyzed FoxA1/2 expression by IHC in human AdSCC (n = 12) to determine whether these transcription factors are differentially expressed between adenocarcinoma and squamous components." (PMID 30475207, 2018). "We recently found that REV-ERBα facilitates FOXA1 chromatin occupancy at non-AR target genes in ARSI-sensitive adenocarcinomas." (PMID 41231955, 2025). "In KrasLSL-G12D/+; Nkx2-1F/F; Foxa2F/F mice, we found that FoxA2 was absent in both components, whereas FoxA1 was expressed in the adenocarcinoma components but absent in the SCC." (PMID 30475207, 2018). "This phenomenon was rarely observed in tumors from other control groups, which predominantly produced intracellular mucin, suggesting that FoxA1 and FoxA2 likely have some specific functions in the regulation of the differentiation state of NKX2-1-negative adenocarcinoma." (PMID 30475207, 2018).
metabolic disease (2 papers, 2024 to 2025). A congenital disorder (due to inherited enzyme abnormality) or acquired (due to failure of a metabolically important organ) disorder resulting from an abnormal metabolic process. "Third, metabolic diseases can be treated by directly knocking out FOXA1 and FOXA2, but this approach also causes the original physiological effects to disappear, leading to side effects such as incomplete organ development and differentiation." (PMID 38605023, 2024). "We should selectively target the upstream regulatory factors of FOXA1 and FOXA2 in metabolic diseases or downstream regulatory factors to achieve therapeutic effects." (PMID 38605023, 2024).
neurodegenerative disease (2 papers, 2016 to 2024). A disorder of the central nervous system characterized by gradual and progressive loss of neural tissue and neurologic function. "Transcriptome profiling of STN neurons in conditional Foxa1 knockout mice revealed changes in gene expression reminiscent of those in neurodegenerative diseases." (PMID 27934886, 2016).
cardiac disease (1 paper, 2024). "There is little evidence about what roles SPI1 and FOXA1 play in cardiac disease." (PMID 38994368, 2024).
inflammation (1 paper, 2018). Aberrant reaction of the microcirculation characterized by movement of fluid and leukocytes from the blood into extravascular tissues. "FoxA1+ Treg cells develop primarily in the central nervous system in response to autoimmune inflammation and have a distinct transcriptional profile." (PMID 30546835, 2018).
FOXA1 also shares sentences with these, for which no sentence is quoted: head and neck squamous cell carcinoma (4 papers); anaplastic thyroid cancer (2); basal cell carcinoma (2); cervical squamous cell carcinoma (2); extramammary Paget disease (2); gallbladder carcinoma (2); kidney cancer (2); metastatic carcinoma (2); Parkinson's (2); acinar adenocarcinomas (1); acne (1); acute leukemia (1); acute respiratory distress syndrome (1); Allergy (1); Bardet-Biedl syndrome (1); brain cancer (1); breast adenocarcinoma (1); breast disease (1); cervical adenocarcinoma (1); chondrosarcoma (1); chronic myeloid leukemia (1); chronic obstructive pulmonary disease (1); ductal carcinoma In situ (1); endocervical adenocarcinoma (1); endometriosis (1); esophageal squamous cell carcinoma (1); Fanconi anemia (1); gallstones (1); gastric tumors (1); glioblastoma (1).
A further 39 diseases each share a sentence with FOXA1 in 1 paper.